RRM2 (ribonucleotide reductase regulatory subunit M2)
Diseases named in the same sentence as RRM2 in open-access papers (continued):
Sharing a sentence is not in itself a finding about the gene and the disease.
breast cancer (continued). "The highest levels of RRM2 and ZWINT were found in HER2-positive breast cancer, and the highest expression of other hub genes was found in triple-negative breast cancer." (PMID 36200070, 2022). "This suggests that up-regulation of RRM2 expression not only affects the OS of breast cancer patients but also affects DMFS, especially for Luminal A subtype breast cancer, the specific mechanism still needs to be further explored." (PMID 35290409, 2022). "Second, it is the first time that the highly expressed RRM2 has poor OS and DMFS in patients with breast cancer with specific molecular subtypes and specific stages." (PMID 35290409, 2022). "To evaluate the role of RRM2 as a prognostic biomarker in breast cancer, we analyzed the relationship between the expression level of RRM2 in the METABRIC database and the overall survival and DMFS of patients with breast cancer." (PMID 35290409, 2022). "In the breast cancer cell lines MCF-7, MDA-MB-231, MDA-MB-453, BT-474, the relative expression level of RRM2 mRNA was significantly up-regulated, compared to the breast epithelial cell line MCF-10A." (PMID 35290409, 2022). "First, 1350 breast cancer samples were downloaded and sorted, and then SPSS statistical software was used to analyze the relationship between the expression level of RRM2 and various clinicopathological characteristics." (PMID 35290409, 2022). "The Kaplan-Meier method was used to study the relationship between the high expression of RRM2 and overall survival and distant metastasis-free survival (DMFS) of breast cancer patients." (PMID 35290409, 2022). "CDC20, TOP2A, RRM2, and UBE2C were highly expressed not only in HCC, but also in breast cancer and other tumors." (PMID 34568357, 2021). "In addition, TTN-AS1 has been shown to promote breast cancer progression by different miRNA/mRNA axes, including miR-524-5p/RRM2 and miR-139-5p/ZEBI, which suggests that the regulatory mechanism of TTN-AS1 in OSCC progression might be involved in multiple molecules." (PMID 34606420, 2021). "High expression of RRM2 was uncovered in glioblastoma with promoting tumorigenicity, prostate cancer, NSCLC, and breast cancer." (PMID 33186389, 2020). "In the current study, we obtained 283 overlapping DEGs and six hub genes (RRM2, CDC20, CCNB2, BUB1B, CDK1, and CCNA2) related to the occurrence and development of breast cancer via comprehensive bioinformatics analysis." (PMID 33083112, 2020). "As a result, there were nearly 2.1% (CDC20, CDK1), 1.2% (RRM2), 0.9% (BUB1B), 0.8% (CCNA2), 0.7% (CCNB2) of breast cancer samples included in cBioPortal had genetic changes." (PMID 33083112, 2020). "At present, evidence of the relationship between RRM2 and CDKN3 in cervical cancer is limited, but their relationship can be found in other cancers, such as hepatocellular carcinoma, breast cancer, renal carcinoma and lung cancer 51-54." (PMID 32922202, 2020). "RRM2 downregulation can overturn AKT-induced tamoxifen resistance and increase therapeutic efficacy in breast carcinoma." (PMID 33411689, 2020). "Western analyses were used to monitor the protein abundances of RRM2, LC3 and p62/SQSTM1, another autophagy marker, in breast cancer cells treated with TMX for 24 and 48 h." (PMID 26675256, 2016). "Here, the RRM2 siRNA was used to inhibit the expression of RRM2 in MDA-MB-231(ER-negative) and ZR-75-1(ER-positive) breast cancer cell lines." (PMID 25213022, 2014). "Cell culture studies also indicate that expression of siRNAs targeting RRM2 significantly reduced the invasion ability in MDA-MB-231 and ZR-75-1 breast cancer cells, which was consistent with our previous studies on other cancers." (PMID 25213022, 2014). "Kaplan-Meier analysis revealed that RRM2 mRNA levels (either 209773_s_at or 201890_at) significantly and negatively impacted the PFS of breast cancer patients in the Pawitan and Ivshina sets." (PMID 25213022, 2014).
breast cancer (continued). "Here, we developed a breast cancer-specific suicide gene circuit (BRAS) that integrates the screened cancer-specific promoters RRM2 and MAFK with a microRNA specific to nontumor cells, utilizing the distinct molecular profiles of tumor and nontumor cells." (PMID 41637060, 2026). "Previous studies have indicated that RRM2 promotes cell proliferation, migration and angiogenesis through the PI3K/AKT pathway and that targeting RRM2 in NSCLC and breast cancer inhibits these processes by reducing PI3K/AKT expression at both the mRNA and protein levels." (PMID 40493217, 2025). "These functional analyses agree on the association of a few genes with breast cancer survival and prognosis, such as DLGAP5, NCAPG, and RRM2, which are not involved in 1CM." (PMID 39125744, 2024). "Here, we focus on circumventing palbociclib resistance by targeting estrogen-receptor-positive (ER+) and estrogen-receptor-negative (ER−) breast cancers with a unique ribonucleotide reductase subtype M2 (RRM2) enzyme inhibitor." (PMID 38473336, 2024). "In this study, we hypothesize that through the inhibition of RRM2, cyclin D1 and the NF-κB pathway, DDX can significantly halt the growth of ER+ and ER− breast cancer cells along with their PLB-resistant counterparts." (PMID 38473336, 2024). "Importantly, the four most important hub genes RRM2, HMMR, EZH2, and CCNB1 appeared to play a significant role in various types of cancer such as non‐small cell lung carcinoma (NSCLC), liver and breast cancer." (PMID 39118438, 2024). "To determine whether palbociclib resistance leads to transcriptional changes, we assessed the mRNA expression of CCND1 and RRM2 in ER+ and ER− parental and PLB-resistant breast cancers." (PMID 38473336, 2024). "In breast cancer cells, the overexpression of AKT could upregulate RRM2 expression, leading to enhanced DNA repair and protection from apoptosis." (PMID 37033615, 2023). "In addition, another RRM2 inhibitor, GW8510, has shown to inhibit the growth of breast cancer and lung cancer." (PMID 35911380, 2022). "Through the BCIP database, we analyzed the expression level of RRM2 in 4 data sets (METABRIC, TCGA Agilent, TCGA RNA-seq, GSE5364), and the results showed that RRM2 expression in breast cancer tissues was significantly up-regulated compared to adjacent normal tissues." (PMID 35290409, 2022). "Although there are some reports of RRM2 regulation in lung and breast cancer, there is no comprehensive molecular understanding of how RRM2 is regulated by key upstream biological processes." (PMID 35911380, 2022). "In this study, we found that ITGB3 knockdown led to a progressive decrease in RRM2 levels, hence we suggest that ITGB3 might be a driver protein for this breast cancer-related protein." (PMID 33083904, 2021). "Other researchers also concluded that altered expression of some genes (RRM2, SPP1, MMP9, Arf1) could be involved in increased cell proliferation of adipose tissue in breast cancer risks." (PMID 34657612, 2021). "High levels of NEAT1, miR-21, and RRM2 have been observed in different breast cancer cell lines, and their elevated levels correlate with poor clinical outcomes, suggesting that the NEAT1/miR-21-RRM2 signaling axis contributes to breast cancer development." (PMID 34527584, 2021). "In breast cancer, the abnormally high expression of TTN-AS1 promotes the proliferation, migration, and invasion of tumor cells by inhibiting mir-524 and promoting the expression level of RRM2." (PMID 34671381, 2021). "Breast cancer patients with positive nodal status (N) showed increased level of RRM2 than those with negative nodal status." (PMID 30898978, 2019). "Conversely, SBR, NPI, HER-2 status, nodal status, basal-like status, and triple-negative status were positively related to RRM2 level in breast cancer samples with respect to normal tissues." (PMID 30898978, 2019). "Breast cancer patients with more advanced SBR grade and NPI tended to express higher RRM2 gene." (PMID 30898978, 2019).
breast cancer (continued). "For example, we showed previously that relative expression of proliferation-related and immune response-related genes, i.e., UBE2C, TOP2A, RRM2, FOXM1, MK167, and BTN3A2, provided a prediction value of adjuvant chemotherapy benefit for patients with ER+/HER2− early breast cancer." (PMID 31779659, 2019). "Here, we have preliminarily demonstrated that inhibition of RRM2 by COH29 could significantly reduce the growth of MCF-7 and MDA-MB-231 breast cancer cells." (PMID 25213022, 2014). "The genes belonged to a variety of biological functions such as cell motility and invasion (Cdc42, ITGB2), cell cycle (EGR1, RRM2) or signal transduction (VEGFC), indicating that expression of E-cadh and P-cadh in breast cancer cells have a significant impact on their overall genetic program." (PMID 19257890, 2009). "FBXO1 was negatively regulated by the E3 ligase (FZR1) and the co-regulator of E3 ligase (FBXL8), which were known to play an oncogenic role in breast cancer, and FBXO1 could inhibit the expression of ribonucleotide reductase M2 (RRM2), a pro-tumorigenic protein." (PMID 35046938, 2021). "Conversely, the Scarff–Bloom–Richardson (SBR) grade, Nottingham prognostic index (NPI), human epidermal growth factor receptor-2 (HER-2) status, nodal status, basal-like status, and triple-negative status were positively related to RRM2 level in breast cancer samples with respect to normal tissues." (PMID 30898978, 2019). "By comparing the RRM2 and KIF11 expression heat map derived from the UCSC Xena web-based tool, it was confirmed that RRM2 expression gradually elevated with increasing KIF11 transcript level, which was determined among a 50-gene qPCR assay (PAM50) breast cancer subtypes in TCGA database." (PMID 30898978, 2019). "We hypothesized that RR subunit M2 (RRM2) might be a novel prognostic and predictive biomarker for estrogen receptor (ER)-negative breast cancers." (PMID 25213022, 2014). "However, not much is currently known about the functional roles of RRM2 in breast cancer (BRCA), and whether BBR regulates the migration and invasion of BRCA cells by regulating the expression of RRM2 remains to be determined." (PMID 36678539, 2022). "Similarly, for early breast cancer, the best three k-gene discriminators are {GPR109B, PCOLCE2, PCSK5}, {PCSK5+COL10A1, FERMT2+SPINT2, MAOA+IGJ}, {COL1A1+PCSK5+TF, GPX3+COL1A1+SPINT2, GPX3+FAP+TMEM97}, and {RRM2+COL1A1+GPR109B+IGJ, RRM2+COL1A1+GPR109B+IGJ, RRM2+COL1A1+GPR109B+SPINT2}, respectively." (PMID 21060876, 2010). "As MDA-MB-468 breast cancer cells already have higher levels of CCND1 and RRM2 expression, we did not observe additional increased expression in these genes with PLB resistance." (PMID 38473336, 2024). "There is almost no copy number variation (CNV) of RRM1 and RRM2 genes in common types of cancers, whereas RRM2B displays CNV gain in more than 3% of breast cancers, liver cancers, stomach cancers and urinary tract cancers." (PMID 31637211, 2019). "Additional associations with MFI found for thioredoxin and downstream factors of the thioredoxin pathway, including PRDX2, RRM2, HIF1A and VEGF, confirm the importance of the thioredoxin system in breast cancer regardless of its ROS-related or unrelated roles." (PMID 20584310, 2010). "Moreover, TMX induced RRM2 reduction was also observed in the ERα-positive breast cancer T47D and MCF7 cells, suggesting that it is not breast cancer subtype is specific." (PMID 26675256, 2016).
lung cancer (61 papers, 2008 to 2025). A malignant neoplasm involving the lung. "RRM2, another gene of interest, is linked to macrophage polarization and lung cancer cell proliferation, and its inhibition induces ferroptosis in lung adenocarcinoma." (PMID 39857625, 2024). "In patients with lung adenocarcinoma (LUAD), low RRM2 was associated with a better prognosis because miR-202-3p inhibited the proliferation and metastasis of lung cancer cells by targeting RRM2." (PMID 38820515, 2024). "Notably, we demonstrate that the biological effects caused by Cyclin Y knockdown can be partially rescued by RRM2, highlighting the significance of the Cyclin Y/RRM2 axis in the regulation of lung cancer progression and radiosensitivity." (PMID 40083692, 2025). "Moreover, alterations in RRM2 are associated with resistance to gemcitabine-induced cell death in lung cancer and pancreatic ductal adenocarcinoma." (PMID 38635758, 2024). "The results demonstrated that the inhibition of RRM2 led to a decrease in lung cancer cell growth and proliferation." (PMID 40083692, 2025). "Rescue experiments confirm that the effects of Cyclin Y on lung cancer are mediated partially by RRM2." (PMID 40083692, 2025). "Animal experiments were conducted to analyze the role of RRM2 in the CHE inhibition of TGF-β-induced lung cancer metastasis." (PMID 40732324, 2025). "Conversely, RRM2 overexpression partially reversed the inhibitory effects on cell growth and proliferation induced by Cyclin Y depletion in lung cancer cells." (PMID 40083692, 2025). "Ribonucleotide reductase regulatory subunit M2 (RRM2) is implied in a variety of cancers, consisting of glioma, bladder cancer, and lung cancer, and correlated with ferroptosis in a GSH-dependent manner." (PMID 39311766, 2024). "RRM2 was identified as a factor influencing the advancement of lung cancer and impacting the infiltration of immune cells within tumors." (PMID 38745285, 2024). "These were consistent with the reported role of RRM2 in tumor progression in other cancers such as lung cancer, glioblastoma and retinoblastoma." (PMID 39243109, 2024). "AFAP1-AS1 regulates lung cancer proliferation, migration, and invasion through the competitive upregulation of RRM2 to inhibit miR-139-5p, IRF7, and RIG-I-like receptor signaling pathways, or epigenetic inhibition of p21 expression." (PMID 38095636, 2023). "Previous studies showed that the overexpression of RRM2 was detected in a wide range of cancers, including lung cancer." (PMID 37508549, 2023). "Numerous studies have observed that RRM2 is overexpressed in many cancers, including renal cell carcinoma, colorectal cancer, lung cancer, bladder cancer, and head and neck cancer, and is regarded as a promoter for cancer progression and therapeutic target." (PMID 37671041, 2023). "Then, we continued to detect the levels of ferrous ion and lipid peroxidation in lung cancer cells after silencing RRM2." (PMID 36153508, 2022). "RRM2, which is highly expressed in lung cancer and related to a poor prognosis, regulates the immune microenvironment of LUAD, which is consistent with our results." (PMID 36153508, 2022). "To detect the expression of RRM2 in normal lung tissues and lung cancer tissues, we performed immunohistochemical experiments for comparison." (PMID 36153508, 2022). "Ribonucleotide reductase subunit M2 (RRM2) has been extensively reported to be involved in the progression of various tumors such as renal cell cancer and lung cancer." (PMID 36304446, 2022). "Others found that the expression level of RRM2 was correlated with invasion, cell differentiation, and metastasis in colorectal carcinoma, and correlated with lung cancer grade level." (PMID 34384030, 2021). "Previous researches on the relationship between RRM2 and lung cancer were too specific but short of a comprehensive view 16-18." (PMID 33123291, 2020). "Low expression of RRM2 has been reported can be used to value the treatment response to platinum-based chemotherapy of lung cancer." (PMID 33123291, 2020).
lung cancer (continued). "In summary, this study provided all-round evidence for the value of RRM2 in the progress of lung cancer and its potential as a bio-target and prognostic predictor of LUAD." (PMID 33123291, 2020). "In particular, the expression level of RRM2 in A549 lung cancer cell line was higher as compared to other lung cancer cell lines, A549 cells thus were selected for the subsequent experiments." (PMID 33411689, 2020). "To further characterize the expression pattern of RRM1, RRM2, and RRM2B in different pathological types and stages of cancer, we chosen lung cancer as a representative cancer type as it is the leading cause of cancer death all over the world." (PMID 31637211, 2019). "In contrast, no study showed down-regulated expression of RRM1 (0 of 19) or RRM2 (0 of 19) in all subtypes of lung cancer, 22.2% (2 in 9) of the Oncomine studies demonstrated a down-regulated RRM2B expression in cases of LUSC and LCLC." (PMID 31637211, 2019). "RRM2 is regulated by the transforming growth factor beta regulator 4 (TBRG4) gene which affects tumorigenesis in human H1299 lung cancer cells." (PMID 31886214, 2019). "The activity of mammalian RNR is mainly controlled by the level of RRM2 and up-regulation of RRM2 in mice leads to lung cancer." (PMID 28507282, 2017). "Immunohistochemistry for RRM1 and RRM2 was performed on a lung cancer tissue microarray (TMA) and analyzed." (PMID 26001082, 2015). "A signature of genes including CDC20, CCNB1, CDC2, CDKN3, MAD2L1, PRC1 and RRM2, were prognostic for 5-year survival in over 400 lung cancer cases, and interestingly, CDC20, CDC2, CCNB1 were also highly overexpressed in the aggressive case." (PMID 22905093, 2012). "Ribonucleotide reductase subunits M1 (RRM1) and M2 (RRM2) are involved in the metabolism of gemcitabine (2′,2′-difluorodeoxycytidine), which is used for the treatment of nonsmall cell lung cancer." (PMID 18414411, 2008). "Recent studies have indicated that low RRM2 expression can inhibit the development of lung cancer." (PMID 40732324, 2025). "Furthermore, we identify RRM2 as a crucial downstream effector of Cyclin Y involved in the biological processes associated with Cyclin Y. These findings suggest that targeting Cyclin Y could serve as a promising approach for enhancing the efficacy of radiotherapy in lung cancer treatment." (PMID 40083692, 2025). "Recent studies have indicated that RRM2 plays a significant role in lung cancer." (PMID 40732324, 2025). "RRM2 was upregulated in multiple tumor types such as lung cancer." (PMID 39243109, 2024). "Expression RRM2 correlates with a poor prognosis in several tumours including lung cancer and PDAC." (PMID 36998446, 2023). "RRM2 has been previously reported as a master driver of tumor aggressiveness and a biomarker of poor prognosis in several cancer including glioma, oral cancer, lung cancer, colorectal cancer, prostate cancer, endometrial cancer and cervical cancer." (PMID 38124207, 2023). "The expression of RRM2 was significantly higher in both lung cancer tissues and cell lines." (PMID 35898471, 2022). "In addition, RRM2 was involved in ferroptosis, and its expression was up regulated in lung cancer tissues and the LUAD cell lines." (PMID 36153508, 2022). "To date, few studies have explored the role of RRM2 in lung cancer." (PMID 36153508, 2022). "In the current study, we disseminated the possible pathways regulated by RRM2 in lung cancer." (PMID 35898471, 2022). "The overall survival of lung cancer patients showed that low RRM2 expression had a better prognosis (p=0.000015), and disease-free survival also suggested that patients with low RRM2 expression had a better prognosis (p=0.019)." (PMID 35898471, 2022). "Similarly, the expression level of RRM2 was significantly higher in lung cancer cell lines (A549, NCL-H292, and Calu-3) compared to normal lung epithelial cell line (BEAS-2B)." (PMID 35898471, 2022).